EZH2 (enhancer of zeste 2 polycomb repressive complex 2 subunit)
Diseases named in the same sentence as EZH2 in open-access papers (continued):
Sharing a sentence is not in itself a finding about the gene and the disease.
pancreatic cancer (continued). "In pancreatic cancer, RAS mutation promotes the expression of EZH2 through activation of the MEK-ERK-ELK1 signaling." (PMID 27793053, 2016). "Either Ring1B or EZH2 knock down independently inhibited tumor growth of pancreatic cancer cells, and simultaneous silencing of Ring1B and EZH2 increased the inhibition ability." (PMID 25431952, 2014). "The over-expression of EZH2 contributes to acquired chemoresistance in ovarian and pancreatic cancer cells." (PMID 25431950, 2014). "Here, we performed immunohistochemistry on tissue microarrays (TMAs) containing 80 pairs of human pancreatic cancer specimens to assess the expression levels of Ring1B, H2AK119Ub1, EZH2, and H3K27Me3 in tumors." (PMID 25431952, 2014). "Combinatorial silencing of Ring1B and EZH2 depleted H2AK119Ub1 and H3K27Me3 in pancreatic cancer cells, enhanced HOX gene derepression, and inhibited tumor cell growth both in vitro and in vivo, indicating the potential link between H2AK119Ub1 and H3K27Me3." (PMID 25431952, 2014). "A recent study has demonstrated that EZH2 represses the cell cycle regulator p27 expression in pancreatic cancer cells, resulting in G1/S arrest." (PMID 25431950, 2014). "Either Ring1B or EZH2 knock down independently inhibited cell proliferation of pancreatic cancer cells, and simultaneous silencing of Ring1B and EZH2 increased the inhibition of cell proliferation." (PMID 25431952, 2014). "Simultaneous silencing of Ring1B and EZH2 via shRNA depleted H2AK119Ub1 and H3K27Me3 in the pancreatic cancer cells PanC1 and AsPC1, enhanced HOX gene derepression, and inhibited tumor cell growth in vitro and in tumor xenograft models." (PMID 25431952, 2014). "As a marker of advanced and metastatic disease in many solid tumors, EZH2 overexpression has been reported in pancreatic cancers, particularly those that are poorly differentiated." (PMID 23940717, 2013). "Clinically, positive correlations have been observed between EZH2 expression and advanced pancreatic cancer stage and grade in patients." (PMID 23940717, 2013). "EZH2 is overexpressed in several malignancies, including major human cancers, such as prostate cancer, breast cancer, pancreatic cancer, renal cell carcinoma, or cervical cancer." (PMID 21765901, 2011). "An interesting study recently demonstrated that EZH2 leads to the repression of the growth-inhibitory p27 cell cycle regulator gene in pancreatic cancer cells." (PMID 21765901, 2011). "This synergistic effect was linked to the suppression of Wnt/β-catenin signaling, suggesting that the EZH2–PPAR axis could serve as a potential therapeutic target in pancreatic cancer." (PMID 41552643, 2026). "This work highlights a complex role for EZH2 in initiation and progression of pancreatic cancer." (PMID 39739419, 2024). "BM-MSCs exosomes could also be loaded with miR-124, which targeted EZH2 in PCCs and sensitized pancreatic cancer to chemotherapy in vitro and in mice models." (PMID 39054529, 2024). "Thus, in combination with other therapeutics, EZH2 inhibitors possess great potential in the treatment of pancreatic cancer." (PMID 36902253, 2023). "ANLN-mediated pancreatic cancer invasion and migration, colony formation, cell proliferation may involve EZH2/miR-218-5p/LASP1 signaling axis." (PMID 37138854, 2023). "Such actions could involve alterations of repressive epigenetic marks since lncRNAs were reported to recruit or to interact with epigenetic writers including DNMTs, and SNHG15 in particular was described to interact with EZH2 in pancreatic cancer." (PMID 37880732, 2023). "In addition, a recent study has reported that STXBP5-AS1 inhibited cancer stem cell phenotypes of pancreatic cancer cells through EZH2/ADGB pathway." (PMID 35802620, 2022). "In addition, lncPVT1 regulates the sensitivity of pancreatic cancer cells to gemcitabine by inhibiting enhancer of zeste homolog-2 (EZH2) at polycomb repressive complex 2 (PRC2), where EZH2 upregulates the expression of lncPVT1." (PMID 35965522, 2022).
pancreatic cancer (continued). "Comparable with our findings in the Panc-1 transplantation model, Ezh2-deficiency did not affect the pancreatic tumor weight of the recipient mice and the survival of the Cas9 Ezh2 KO transplanted mice was even reduced compared to Cas9 Ctrl animals." (PMID 35884510, 2022). "Enhancer of zeste homolog 2 (EZH2) is abnormally highly expressed in pancreatic cancer (PC)." (PMID 34335707, 2021). "Interestingly, PVT1 has been found to form a complex with EZH2, a key step in the development of gemcitabine resistance in pancreatic cancer." (PMID 34564701, 2021). "Similarly, in pancreatic cancer, EZH2 promoted EMT and distant metastasis by mediating microRNA-139-5p." (PMID 33569740, 2021). "Moreover, EZH2 is able to upregulate the expression of miR-139 by promoting the tri-methylation of H2K27 in pancreatic cancer cells." (PMID 33901015, 2021). "miR-124 delivered by bone marrow mesenchymal stromal cell-derived exosomes can directly inhibit the expression of EZH2, and consequently suppress the malignant phenotypes of pancreatic tumor cells, and sensitizes pancreatic cancer cells to chemotherapy in vitro and in vivo." (PMID 34868904, 2021). "Our findings suggest that HAT1-induced gemcitabine resistance in pancreatic cancer may be mediated by the PVT1/EZH2 complex." (PMID 34564701, 2021). "PVT1 had also been shown to bind EZH2, it was consistent in pancreatic cancer cells." (PMID 34564701, 2021). "Importantly, EZH2 has been shown to promote drug resistance by suppressing p27Kip1 expression in pancreatic cancer cells." (PMID 34564701, 2021). "Similarly, FBW7-dependent ubiquitination and degradation of EZH2 is found in the pancreatic cancer cells and prevents cancer migration and invasion." (PMID 34802056, 2021). "In addition, metformin also upregulates let-7 family, miR-200 family, miR-101 and Oct4, Notch-1, and EZH2 mRNAs in pancreatic cancer cells." (PMID 32512882, 2020). "In the present study, it was found that miR-124 could induce the apoptosis and suppress the cell invasion, migration and EMT of pancreatic cancer cells, and miR-124 and these effects could be partly restored by EZH2 overexpression." (PMID 33040049, 2020). "Furthermore, EZH2 is a histone methyltransferase that catalyzes the methylation of H3K27me3 in pancreatic tumors, and has been considered as a downstream gene of K-Ras." (PMID 33040049, 2020). "Furthermore, the expression levels of miR-124 in each pancreatic cancer cell line were all notably lower, while the EZH2 expression were upregulated than that in HPDE6." (PMID 33040049, 2020). "Thus, TUG1/EZH2 triggers anti-apoptosis during pancreatic cancer by silencing its tumor-suppressive target genes." (PMID 33050646, 2020). "In a pancreatic cancer cells experiment, exogenous overexpression of EZH2 resulted in increased expression of the mesenchymal marker Vimentin and decreased epithelial marker E-cadherin level, while EZH2 knockdown resulted in decreased expression of Vimentin and increased expression of E-cadherin." (PMID 32723346, 2020). "For example, EZH2 induces histone methylation and heterochromatin formation at miR-218-2 promoter that leads to miR-218 downregulation in pancreatic cancer, thereby mediating cell proliferation, cell migration and cell invasion in vitro and tumor growth and metastasis in vivo." (PMID 31395079, 2019). "Other studies have found that ANLN could promote the progression of pancreatic cancer by inducing the up-regulation of EZH2 by mediating the mir-218-5p /LASP1 signaling axis." (PMID 31681575, 2019). "Taken together, EZH2 induced by ANLN may promote pancreatic cancer progression by regulating miR-218-5p/LASP1 signaling axis." (PMID 31395079, 2019). "Moreover, a subset of patient-derived organoids displayed sensitivity toward EZH2 inhibition, suggesting the potential of EZH2 blockage for pancreatic cancer treatment, possibly in a model of personalized medicine based on an organoid platform." (PMID 31238554, 2019).
pancreatic cancer (continued). "In vivo, EZH2 knockdown decreases pancreatic tumor growth and liver metastasis." (PMID 31238554, 2019). "Taken together, ANLN may promote pancreatic cancer cell growth, migration and invasion by regulating EZH2/miR-218-5p/LASP1 signaling axis." (PMID 31395079, 2019). "In pancreatic cancer, EZH2 negatively regulates p27Kip1 expression in a RelB:p52-dependent manner." (PMID 31277415, 2019). "In summary, we have identified the ANLN/EZH2/miR-218-5p/LASP1 signaling axis in pancreatic cancer cells, which provides new insights into the mechanism underlying pancreatic cancer progression and generates a mechanism-based novel framework for developing therapeutics in pancreatic cancer treatment." (PMID 31395079, 2019). "Analysis of changes in gene expression after MALAT-1 knockdown shows that this lncRNA represses several tumor suppressor-like genes including N-myc downregulated gene-1 (NDRG-1), a tumor suppressor in pancreatic cancer that is also corepressed by EZH2 (a PRC2 complex member)." (PMID 29389953, 2018). "Third, EZH2 is a bona fide substrate of FBXW7 in pancreatic cancer cells." (PMID 30150556, 2018). "EZH2 is a fundamental and necessary contributor to pancreatic cancer cell stemness." (PMID 29710783, 2018). "Interestingly, EZH2 has been reported to be a substrate of FBXW7 in pancreatic cancer cells and is negatively correlated with FBXW7 expression in human pancreatic cancer samples." (PMID 30086763, 2018). "In addition, depletion of EZH2 induces expression of p27 and decreases cell proliferation in pancreatic cancer cells." (PMID 28561778, 2017). "We found that silencing EZH2 increased E-cadherin expression in pancreatic cancer." (PMID 26848980, 2016). "Moreover, EZH2 expression correlated inversely with E-cadherin expression in pancreatic cancer tissue samples, and overall survival among patients with high EZH2 expression and low E-cadherin expression was the shortest." (PMID 26848980, 2016). "Together, these findings demonstrated that EZH2 expression could be an independent prognostic marker for pancreatic cancer." (PMID 26848980, 2016). "Notably, a combinatorial pattern of high EZH2 expression and low E-cadherin predicted the worst clinical prognosis in pancreatic cancer." (PMID 26848980, 2016). "EZH2 could therefore be an independent prognostic factor for pancreatic cancer patients as well as a novel and efficient molecular target for pancreatic cancer therapies." (PMID 26848980, 2016). "Thus, EZH2-si1 was used to examine the effects of decreased EZH2 expression on pancreatic cancer cell proliferation." (PMID 26848980, 2016). "Tissue microarrays (TMAs) were used to evaluate the EZH2 expression in pancreatic cancer." (PMID 26848980, 2016). "We next began to explore the molecular functions of EZH2 in pancreatic cancer cell lines." (PMID 26848980, 2016). "Moreover, we found that increased EZH2 expression was an independent negatively predictive factor for pancreatic cancer patients' clinical outcomes." (PMID 26848980, 2016). "To further assess the phenotype of the Ring1B- and EZH2-knocked down pancreatic cancer cells, we performed a cell proliferation assay to determine whether Ring1B and EZH2 are essential for tumor cell proliferation in vitro." (PMID 25431952, 2014). "Since we established that Ring1B and EZH2 are required for pancreatic cancer cell proliferation in vitro, a nude mice-based subcutaneous xenograft model was performed next to investigate the in vivo activity of Ring1B and EZH2 on the tumor growth of PanC1 cells." (PMID 25431952, 2014). "In vivo, suppressing EZH2 diminished tumorigenicity and inhibited pancreatic cancer metastasis." (PMID 23940717, 2013). "EZH2 is a known oncogene for a large number of tissues, including pancreatic cancer." (PMID 23448518, 2013).
pancreatic cancer (continued). "Similarly, knockdown of EZH2 resulted in a significant decrease in cellular proliferation and invasiveness and sensitized pancreatic cancer cells to doxorubicin and gemcitabine, revealing the potential of an EZH2 inhibitor-chemotherapeutic combination therapy." (PMID 23940717, 2013). "We furthermore tested whether EZH2 may repress the growth-inhibitory p27 gene, as reported for pancreatic cancer." (PMID 21765901, 2011). "Also, update research has highlighted that EZH2-mediated H3K27m3 blockade of cyclin-dependent kinase inhibitor 1C could suppress glycolysis, proliferation and migration of pancreatic cancer cells." (PMID 35414117, 2022). "Finally, we proceeded to determine whether HPSC-EXO affects the chemotherapy resistance of pancreatic cancer through the lncRNA UCA1/EZH2/SOCS3 axis." (PMID 34868904, 2021). "Also, EZH2 mediates EMT of pancreatic cancer (PC) by binding with miR-139-5p." (PMID 34992654, 2021). "In addition, EZH2 has been considered to be critical for pancreatic cancer." (PMID 33040049, 2020). "Furthermore, the elevated expression of miR-124 in AsPC-1 and PANC1 via miR-124 mimic transfection-induced apoptosis, metastasis and epithelial mesenchymal transition was suppressed, and the EZH2 overexpression partly reversed the protective effects of miR-124 against pancreatic tumors." (PMID 33040049, 2020). "EZH2/miR-139-5p could be a therapeutic strategy for the treatment of pancreatic cancer." (PMID 31602269, 2019). "Moreover; MiR-139-5p transcription is inhibited by EZH2 through up-regulating H3K27me3, thereby downregulation of EZH2 and up-regulation of miR-139-5p impede extracellular matrix and lymph node metastasis in pancreatic cancer." (PMID 31602269, 2019). "Thus, we hypothesized that ANLN may induce the silencing of miR-218-5p by mediating EZH2 in pancreatic cancer progression." (PMID 31395079, 2019). "Our results show that EZH2-based therapies may be an option for the treatment of pancreatic cancer." (PMID 26848980, 2016). "Consequently, EZH2 may be a significant prognostic value for overall survival in pancreatic cancer patients." (PMID 23940717, 2013). "Interestingly, it was recently reported that EZH2 depletion led to p27 re-expression in pancreatic cancer cells, indicating that EZH2 may contribute to tumor cell proliferation by repressing p27." (PMID 21765901, 2011). "BLACAT1 inhibits the trimethylation of H3K27 on the CDKN1C gene by blocking the recruitment of EZH2, thereby promoting the expression of CDKN1C and inhibiting the expression of CCNE, and thus suppressing the biological processes of pancreatic cancer cells." (PMID 40778223, 2025). "For example, EZH2 inhibitors can enhance the production of SASP chemokines and potentiate NK and T cell–mediated immune responses in models of pancreatic cancer." (PMID 39813356, 2025). "TCDD exposure resulted in a significant increase in MALAT1, EZH2, and H3K27me3 levels but exposure to AhR antagonists exhibited the reversed functions of MALAT1, EZH2, and H3K27me3 in AhR-overexpressing pancreatic cancer cells." (PMID 40765830, 2025). "More recent studies show that EZH2 deletion in pancreatic cancer cells increased GATA6 expression, a marker of classical PDAC subtype, indicating the presence of EZH2 promotes a more aggressive, basal-like PDAC subtype." (PMID 39739419, 2024). "Nevertheless, as many studies have emphatically shown that CDK5 is critical for pancreatic cancer progression, the clinical significance of CDK5-mediated EZH2 degradation needs to be explored further." (PMID 37993880, 2023). "In another study, EZH2 was shown to promote glycolysis in pancreatic cancer mediated by H3K27me3 and the suppression of LINC00261, which acts as a tumor suppressor in pancreatic cancer." (PMID 36979019, 2023). "DUXAP8 promoted the cell proliferation and tumor progression in pancreatic cancer through p21 and KLF2 down regulations following interaction with EZH2 and LSD1." (PMID 37807067, 2023).
pancreatic cancer (continued). "In pancreatic cancer, active CDK5 phosphorylates enhancer of zeste homolog 2 (EZH2), which triggers its degradation via FBW7, a component of ubiquitin ligase." (PMID 37993880, 2023). "As EZH2 degradation inhibits tumor migration and invasion, CDK5 acts as a tumor suppressor in pancreatic cancer." (PMID 37993880, 2023). "IRAIN induced cell proliferation directly through interacting with EZH2 and LSD1 complexes and suppressing KLF2 and P15 in pancreatic cancer cells." (PMID 37807067, 2023). "SNHG15 induced pancreatic cancer cell proliferation by repressing P15 and KLF2 expression via EZH2-related H3K27me3." (PMID 37807067, 2023). "It has been reported that curcumin administration can promote sensitivity of pancreatic cancer cells to gemcitabine via regulating the expression level of PVT1 and its interaction with EZH2." (PMID 35236381, 2022). "However, EZH2 may also function as a tumor suppressor in myeloma and pancreatic tumor." (PMID 35269532, 2022). "The lncRNA taurine upregulated gene 1 (TUG1) cooperates with EZH2 to down-regulate miRNA-382 and aid in sponging, leading to EMT induction and pancreatic cancer invasion." (PMID 35236381, 2022). "Enhancer of zeste homolog 2 (EZH2), a substrate of FBXW7, figures as an oncogenic protein facilitating invasion and metastasis of pancreatic cancer cells, which can be abrogated by CDK5/FBXW7-dependent degradation." (PMID 35515121, 2022). "SOX8 transcriptionally regulated EZH2, which reduced expression of SPARC by promoting the methylation of SPARC, thereby reducing the transport of albumin-bound paclitaxel in pancreatic cancer cells." (PMID 35173526, 2022). "In this way, curcumin suppresses the expression of EZH2 as a subunit of PRC2 and its related lncRNA PVT1 to prevent pancreatic cancer progression and increase gemcitabine sensitivity." (PMID 35236381, 2022). "In pancreatic cancer, long-term exposure to 5-HT in an autocrine or paracrine manner induced PRC2-independent EZH2 action that supported the TPH1-5-HT7 axis, leading to gemcitabine resistance and a CSC population increase." (PMID 34771469, 2021). "HOTAIR worked synchronously with EZH2 and transcriptionally downregulated DR5 in pancreatic cancer cells." (PMID 34178644, 2021). "This study aims to investigate roles of lncRNA UCA1-loaded exosomes secreted by pancreatic stellate cells (PSCs) in Gemcitabine (Gem) resistance of pancreatic cancer under hypoxia, which involves the methylation of SOCS3 and EZH2 recruitment." (PMID 34868904, 2021). "This study suggests that HAT1 regulates the sensitivity of pancreatic cancer to gemcitabine by regulating PVT1/EZH2 complex, highlighting the importance of HAT1 in the development of gemcitabine resistance in pancreatic cancer." (PMID 34564701, 2021). "In this study, we found histone acetyltransferase 1 (HAT1) enhanced the tolerance of pancreatic cancer cells to gemcitabine and HAT1-mediated resistance mechanisms were regulated by PVT1 and EZH2." (PMID 34564701, 2021). "Other pathways linking EZH2 and EMT described in other tumor types, such as the Sox4/Ezh2 axis in pancreatic cancer or the EZH2-mediated WNT5A silencing in colon cancer, remain to be proven." (PMID 34199763, 2021). "AGAP2-AS1 worked synchronously with EZH2 (enhancer of zeste homolog-2) and epigenetically inhibited ANGPTL4 and ANKRD1 and fueled proliferation and metastasis of pancreatic cancer cells." (PMID 34178644, 2021). "Detailed mechanistic insights revealed that HOXA-AS2 interacted directly with EZH2 (enhancer of zeste homolog-2) and lysine specific demethylase 1 (LSD1) and synchronously promoted growth ability of pancreatic cancer cells." (PMID 34178644, 2021). "The exosomes were isolated from PSCs and hypoxic PSCs (HPSCs), and co-cultured with pancreatic cancer cells transduced with manipulated lncRNA UCA1, EZH2, and SOCS3." (PMID 34868904, 2021).